IVL (involucrin)
Description:
Part of the insoluble cornified cell envelope (CE) of stratified squamous epithelia.
Tractability: Antibody: its Gene Ontology location is reachable by antibodies, with high confidence.
Gene: Protein-coding gene on chromosome 1 (152,908,546 to 152,911,886, forward strand). Ensembl gene ENSG00000163207.
Subcellular location: Cytoplasm
Subcellular location (Human Protein Atlas): Cytosol; Centrosome; Nuclear bodies
Pathways (Reactome):
Developmental Biology: Differentiation of Keratinocytes in Interfollicular Epidermis in Mammalian Skin; Formation of the cornified envelope
Gene Ontology:
Molecular function: protein binding
Biological process: keratinocyte differentiation; peptide cross-linking; response to UV-B; isopeptide cross-linking via N6-(L-isoglutamyl)-L-lysine; keratinization
Cellular component: cornified envelope; cytoplasm; cytosol; extracellular exosome
Genetic constraint (gnomAD): Loss-of-function variants: 0 observed, 0.19 expected, observed/expected ratio (o/e) 0, 90% interval 0 to 1.88. That is too few expected variants to judge how well the gene tolerates losing a copy. Missense variants: 717 observed, 594.14 expected, observed/expected ratio (o/e) 1.21, 90% interval 1.13 to 1.28. Synonymous variants: 256 observed, 259.73 expected, observed/expected ratio (o/e) 0.99, 90% interval 0.89 to 1.09.
Homologues: Orthologues: chimpanzee IVL (87% identical), macaque IVL (66% identical), pig IVL (31% identical), dog IVL (23% identical).
Diseases named in the same sentence as IVL in open-access papers:
IVL is named in the same sentence as 70 diseases in open-access papers, as found by Europe PMC text mining. Sharing a sentence is not in itself a finding about the gene and the disease. The quoted sentences say what the papers report.
psoriasis (40 papers, 2009 to 2026). An autoimmune condition characterized by red, well-delineated plaques with silvery scales that are usually on the extensor surfaces and scalp. "However, this mouse model did display decreased expression of loricrin and upregulation of involucrin, which are alterations typically associated with psoriasis." (PMID 39282523, 2024). "In the psoriasis–AD overlap, cytokines linked to Th1, Th17, and Th22 responses in psoriasis help downregulate the expression of filaggrin (FLG), loricrin (LOR), and involucrin (IVL)." (PMID 39859462, 2025). "The elevated involucrin expression has similarly been found in atopic dermatitis and psoriasis, indicating impaired epidermal differentiation, which is also noted in HS." (PMID 40225748, 2024). "It was observed there was an increase in the content of both involucrin and filaggrin, which are usually disturbed in psoriasis patients, in addition to skin irritation studies which proved that no adverse effects or itching were observed upon using VCO." (PMID 36986611, 2023). "Filaggrin and loricrin, which participate in the formation of epidermal cornified envelopes, are decreased in psoriasis, whereas involucrin, another envelope precursor, is overexpressed in psoriasis lesions." (PMID 37111171, 2023). "LCN2 is highly expressed in the skin lesions and the serum of patients with psoriasis and can inhibit the synthesis of keratin, involucrin, and loricrin in KCs, leading to epidermal parakeratosis via the Tcf7L1-lipocalin 2 signaling axis." (PMID 36950008, 2023). "The increased expression of PCNA and involucrin suggests the presence of hyperkeratosis and parakeratosis, the typical pathological features commonly observed in psoriasis." (PMID 37465147, 2023). "Oscillibacter was positively correlated with keratin 17 and involucrin and negatively correlated with loricrin, indicating that it was contributing to psoriasis development." (PMID 37111171, 2023). "IVL is expressed in the spinous layer in normal human skin, and its expression is usually increased in psoriasis." (PMID 35745702, 2022). "With the accelerated differentiation process in psoriasis, the expression of precursor proteins such as IVL is increased and persistent throughout the suprabasal layers." (PMID 35745702, 2022). "There, the authors attributed the high AF intensity of psoriasis to abnormal keratinization among other factors, such as increased involucrin levels and increased collagen production." (PMID 33562614, 2021). "In psoriasis, there is an increased expression of involucrin, a precursor protein that leads to abnormal keratinocyte differentiation, PTU attributable to the downregulation of involucrin in psoriasis." (PMID 33585138, 2021). "Increased expression of IVL correlates with undesirable outcomes of squamous cell carcinoma, and IVL contributes to inflammatory skin diseases such as psoriasis." (PMID 32934956, 2020). "The early expression of involucrin was described in other hyperproliferative diseases, such as psoriasis and PPK, but an ECS staining pattern for both proteins has not been described before." (PMID 32333380, 2020). "In psoriasis, Involucrin and TGase 1 are proteins expressed in the early stages of keratinocyte differentiation." (PMID 32795328, 2020). "In psoriasis, the early differentiation marker involucrin is highly expressed, while the other early differentiation factor, keratin 1, and the late differentiation marker, loricrin, are downregulated." (PMID 30544700, 2018). "We modeled this aberrant mTOR activation using the synthetic mTOR agonist MHY 1485, which induced psoriasis-like skin changes especially skin thickening and delocalization of involucrin." (PMID 28700632, 2017). "In the psoriasis-like skin, involucrin mRNA expression was significantly reduced compared to the control skin." (PMID 26355594, 2015). "This resembles the ectopic involucrin expression pattern previously reported in psoriasis, epidermal tumours, and cultured skin substitutes." (PMID 24023889, 2013).
psoriasis (continued). "To model the suprabasal expression of PPARβ/δ observed in psoriasis in humans, we initially intended to target transgenic PPARβ/δ expression using a “conventional” promoter active in suprabasal epidermis, e.g. the involucrin promoter." (PMID 20300524, 2010). "Furthermore, vitamin D contributes to skin barrier integrity by upregulating proteins like filaggrin and involucrin, addressing a common deficit in psoriasis." (PMID 39796035, 2024). "To assess whether FZHFZY influences epidermal differentiation in the skin of mice with IMQ-induced psoriasis, we detected the expression of loricrin, filaggrin, involucrin, keratin 5, keratin 14 and keratin 15 in the skin by RT-PCR and western blotting." (PMID 34456715, 2021). "The dysregulated expression of FLG, FLG2, LOR, and IVL is known to be normalized by specific biologic treatments, for example, blockade of interleukin-4 (IL-4) and IL-13 in AD or blockade of IL-17A in psoriasis." (PMID 32751111, 2020). "The CHi-C data showed multiple, robust interactions between the psoriasis-associated regions at the LCE genes, including from within the 32-kb LCE3C/B-del region, and genes downstream in the EDC that included IVL, LOR, PRR9 and SPRR genes, over a distance of ~ 600 kb." (PMID 32366252, 2020). "Consistently, the results of the present study revealed an obvious decrease in CK10 production and increased Involucrin expression in skin biopsies of psoriasis patients, which is likely to be responsible for a significant suppression of keratinocyte differentiation." (PMID 30219085, 2018). "Similarly, AHR activation in keratinocytes restores the skin barrier by upregulating epidermal differentiation genes (loricrin and involucrin) and inhibits oxidative stress via Nrf2 signaling, thereby alleviating skin disorders like psoriasis and atopic dermatitis." (PMID 41513604, 2026). "Therefore, recovery of filaggrin and involucrin, which are reduced in AD conditions, may help in relieving symptoms such as skin dryness, erythema, psoriasis, and desquamation." (PMID 34204204, 2021). "Because of the thinning or disappearance of the granular layer at psoriasis lesions, the spinous layer may prematurely express the products (such as fatty acid-binding protein, filaggrin, corneodesmosin, glutaminase, involucrin, and loricrin) normally expressed in the granular layer." (PMID 33967781, 2021). "In our study, there is downregulated expression of loricrin, filaggrin and involucrin, but elevated expression of keratin 5, keratin 14 and keratin 15 in IL-17A/IL-22/IFN-γ/TNF-α–induced HaCaT cells and in mice with IMQ-induced psoriasis." (PMID 34456715, 2021). "The gene expression of FLG, FLG2, LOR, IVL, and S100A7 is differentially affected in atopic dermatitis (AD) and psoriasis." (PMID 32751111, 2020). "Together with the elevated CEBPB gene expression, the expression of keratinocyte terminal differentiation genes, such as IVL, FLG2, and TGM1, is upregulated in the lesional skin of psoriasis." (PMID 32751111, 2020). "IVL, OASL, and ISG15 were also the potential gene targets of the drugs for treating psoriasis in this study." (PMID 32669126, 2020). "Some of the genes found to be commonly upregulated in psoriasis and skin SCC, such as ADAM23, Krt16 (cytokeratin 16) and IVL (involucrin), were also found to be upregulated in 3 week TPA treated skin (data not shown)." (PMID 19432991, 2009). "Finally, PPI network analysis demonstrated that CXCL10 was the hub gene with the highest degree, and CXCR2, CXCL10, IVL, OASL, and ISG15 were the potential gene targets of the drugs for treating psoriasis." (PMID 32669126, 2020). "Of these genes, IVL interacted with psoriasis baits in unstimulated but not in stimulated HaCaT cells, and its expression decreased upon stimulation (FC = 0.40; adj." (PMID 32366252, 2020). "Besides, some psoriasis-related genes such as SPRR genes, HSD11B1, GGH, CXCR2, IVL, OASL, ISG15, and CXCL10 may be important targets in psoriatic therapy." (PMID 32669126, 2020).
psoriasis (continued). "In addition, genes involved in epidermal differentiation, including IVL, TGM, SPRR2A/B/E/G, SERPINB7/8, are induced in DM (red bar), which have also been shown to be elevated in other inflammatory skin diseases, such as psoriasis and atopic dermatitis." (PMID 22235269, 2012). "No tendency for divergent gene expression of FLG, FLG2, IVL, LOR or HRNR in GATA3 silenced cells when compared to control cells was visible under psoriasis-like conditions." (PMID 28928464, 2017). "The results show that the expression of Involucrin and Filaggrin in the epidermis of let-7bTG mice are not significantly different in normal skin, whereas we observed decreased expression of let-7b in the IMQ-induced psoriasis mouse model." (PMID 30219085, 2018).
atopic dermatitis (15 papers, 2012 to 2026). "IVL also one of the CE proteins synthesized by keratinocyte, showed reduced expression in the lesional skin of atopic dermatitis patients." (PMID 39107974, 2024). "According to the literature, involucrin and human β-defensin-2 seemed to be good candidates for differentiation between atopic dermatitis and psoriasis vulgaris, as their higher concentrations were described in psoriasis vulgaris." (PMID 39273140, 2024). "At the mRNA expression level, we observed that only involucrin was markedly downregulated in NC/Nga mice with atopic dermatitis compared to the control group, and its expression was significantly restored by calcitriol application." (PMID 37298299, 2023). "The expression of filaggrin, involucrin, and loricrin was decreased in the epidermis of NC/Nga mice with atopic dermatitis." (PMID 37298299, 2023). "Immunohistochemical analysis showed that filaggrin, involucrin, loricrin, claudin-1, occludin, and ZO-1 were decreased in NC/Nga mice with atopic dermatitis, which is consistent with previous reports." (PMID 37298299, 2023). "Reduced expression of components of the cornified envelope, loricrin, filaggrin and involucrin are frequently down-regulated in human atopic dermatitis." (PMID 34445339, 2021). "For instance, as described in atopic dermatitis, T helper type 2-produced cytokines (especially IL-4 and IL-13) affect keratin, desmoglein, loricrin and involucrin levels." (PMID 32119674, 2020). "Previous literature reported that mRNA and protein expression of IVL significantly reduced when the skin barrier function was impaired, yet some studies showed that IVL was upregulated in patients with atopic dermatitis." (PMID 28085100, 2017). "The main objective of our work was to differentiate between healthy skin (C), atopic dermatitis (AD) and psoriasis vulgaris (PV) biopsies on the base of involucrin (IVL) and human β-defensin-2 (hBD-2) concentrations and their mRNA, as well as mRNA for TPP2 and PSMB8." (PMID 39273140, 2024). "Based on our findings it may be inferred that dogs with atopic dermatitis manifest skin lesions along with the inflammatory response, and the skin barrier proteins (Filaggrin and Involucrin) and inflammatory cytokines (TNF-α, IL-31, IL-13) seem to be key players in the pathogenesis of AD in dogs." (PMID 34075152, 2021). "In patients with atopic dermatitis, it has been reported that the mRNA expression of filaggrin, loricrin, occludin, and claudin-1 was decreased, while the expression of involucrin and TJP1 was not affected compared with control subjects." (PMID 37298299, 2023). "At the mRNA level, involucrin and occludin were downregulated, while the expression of filaggrin, loricrin, claudin-1, and Tjp1 was not changed in NC/Nga mice with atopic dermatitis." (PMID 37298299, 2023). "The evident expression of filaggrin and involucrin in lesional skin does not support a pathogenesis of atopic eczema." (PMID 32333380, 2020).
squamous cell carcinoma (10 papers, 2004 to 2024). A carcinoma arising from squamous epithelial cells. "IVL was significantly downregulated in cervical intraepithelial neoplasia and ultimately squamous cell carcinoma." (PMID 39060960, 2024). "Involucrin has earlier been suggested as a promising marker of tumor differentiation and survival in squamous carcinoma of the larynx." (PMID 34283070, 2021). "Papillomas exhibited regular involucrin expression - similar to that in normal squamous epithelium while squamous cell carcinomas showed an irregular distribution of involucrin." (PMID 26337468, 2015). "In poorly differentiated squamous cell carcinomas, involucrin immunostaining is generally weak even in tumour regions that avidly bind pimonidazole." (PMID 14760391, 2004). "Although involucrin had not been identified previously as an ORP, c-Jun/AP-1 is known to be responsive to hypoxia in squamous cell carcinoma cells and it was conceivable that involucrin expression was oxygen regulated." (PMID 14760391, 2004). "The majority of hypoxic cells in squamous cell carcinomas of the head and neck and cervix express involucrin, a molecular marker for differentiation." (PMID 14760391, 2004). "The induction of involucrin during hypoxic exposure of SCC9 cells in suspension culture confirms that involucrin can be induced by hypoxia in moderately differentiated squamous cell carcinoma cells." (PMID 14760391, 2004). "Previous findings have suggested that involucrin is a biomarker of EMT in squamous cell carcinoma." (PMID 35054979, 2022). "The rapid rate of induction, steep pO2 dependence and high Km could be important in understanding immunostaining patterns for involucrin in squamous cell carcinomas." (PMID 14760391, 2004). "Hypoxia inhibits differentiation in some cell lines and possibly in breast carcinomas, but the association between hypoxia and involucrin expression indicates that this might not be true for squamous cell carcinomas." (PMID 14760391, 2004). "The present investigation examines whether involucrin is oxygen regulated in an in vitro model comprising moderately differentiated SCC9 and poorly differentiated SCC4 squamous cell carcinoma cells." (PMID 14760391, 2004). "Cell lines derived from a poorly differentiated squamous cell carcinoma, for example, can express involucrin without losing proliferative capability." (PMID 14760391, 2004). "Clearly, the presence of involucrin need not be a sign of end stage differentiation and further work will be required to define the extent to which hypoxic cells in squamous cell carcinomas are differentiated." (PMID 14760391, 2004). "We searched for markers which can specifically detect this CK5/IVL double-negative population and focused on aquaporin-5 (AQP5) which is expressed in normal epidermis and epithelial cells of airways, and in squamous cell carcinoma of the oral cavity." (PMID 34934075, 2021).
melanoma (9 papers, 2016 to 2025). A malignant, usually aggressive tumor composed of atypical, neoplastic melanocytes. "Kaplan–Meier survival analyses showed that FLG, KRT5, DSG1, DSG3, and IVL expression levels were significantly associated with melanoma patient survival (p < 0.01)." (PMID 33178610, 2020). "Some of the genes, such as LOR, SPRR1B, and IVL, were even undetectable in metastatic melanoma tissue." (PMID 35003328, 2021). "In general, the hub genes, including KRT5, IVL, and DSP, and key pathways associated with melanoma metastasis defined in the present study may provide new insights into clinical melanoma treatment." (PMID 35054979, 2022). "Overall, this systematic meta-analysis of gene profiling was a step forward in the investigation of the mechanisms underlying melanoma's metastasis, and the role of SPRR1B, SPRR2B, TGM1, CDSN, and IVL in keratinocyte differentiation GO term needs to be further studied." (PMID 35003328, 2021). "Transcription profiles of FABP5, IVL, KRT6A, KRT15, KRT16, and TIMP2 provided clues of prognostic implications, which might help us evaluate malignant potential of nevus and underlying carcinogenesis progress from melanocytic nevus to melanoma." (PMID 32934956, 2020). "Expression profiles of FABP5, IVL, KRT6A, KRT15, KRT16, and TIMP2 provide clues of prognostic implications, which might help us evaluate malignant potential of nevus and underlying carcinogenesis progress from melanocytic nevus to melanoma." (PMID 32934956, 2020). "In the present study, the downregulation of the KRT5, IVL, and DSP expressions implied inhibitory effects of these genes in melanoma metastasis." (PMID 35054979, 2022). "Further, alterations in the expression profiles of FABP5, IVL, KRT6A, KRT15, KRT16, and TIMP2 were significantly associated with worse prognosis, indicating that these hub genes may participate in the aggressive transformation from a nevus to malignant melanoma." (PMID 32934956, 2020). "Five key genes FLG, DSG1, DSG3, IVL, and EGFR were identified in the TCGA database and melanoma tissues." (PMID 33178610, 2020). "Initially, we plotted the expression of three genes which are tightly restricted to the keratinocyte lineage (IVL, KRT14 and BNC) for the 473 melanoma samples within the TCGA RNA sequencing dataset." (PMID 27340778, 2016). "The enrichment of these categories reflects the dysregulation of transcriptional programs typical of keratinocytes (e.g., SPRR1/2/3, KRT10/KRT16, LOR, IVL, EVPL, SCEL, TGM1/TGM3, CERS3, ACER1, DSP) and, above all, the epithelial crosstalk that influences melanoma biology." (PMID 41465101, 2025). "Overall, KRT5, IVL, and DSP might represent potential functions for the prevention and treatment of melanoma metastasis." (PMID 35054979, 2022). "In this study, we highlighted that KRT5, IVL, and DSP may serve as novel targets to suppress melanoma metastasis." (PMID 35054979, 2022). "The results suggested that FLG, DSG1, DSG3, IVL, and EGFR might play important roles and potentially be valuable in the prognosis and treatment of melanoma." (PMID 33178610, 2020). "In addition, survival curves indicated that six hub genes, including FABP5, IVL, KRT6A, KRT15, KRT16, and TIMP2, were significant prognostic signatures for CM and of significant value to predict transformation from nevi to melanoma." (PMID 32934956, 2020). "It is noticeable that the functional characteristics of KRT5, IVL, and DSP in melanoma have not been fully explored, especially in melanoma metastasis." (PMID 35054979, 2022).